TGFB1 (transforming growth factor beta 1)
Diseases named in the same sentence as TGFB1 in open-access papers (continued):
Sharing a sentence is not in itself a finding about the gene and the disease.
cancer (continued). "TGFβ1-induced invasion of cancer cells into collagen type 1 was assessed using a 3D cell culture chip, and the invasive potential of enhanced CLOCK-expressing 4T1 cells was lower than that of Mock-transduced 4T1 cells (p<0.01)." (PMID 33890571, 2021). "We used recombinant TGFβ1 either individually or in combination with RUNX1 inhibitor (Ro5-3335) to treat the cancer cells for 24 h." (PMID 34376784, 2021). "In the case of resistance to PDT, CAF-derived TGFβ1 has been identified as an extrinsic factor in different cancers, including cSCC." (PMID 34830768, 2021). "CAFs are routinely generated either through surgical extraction from cancer patients or by activation of normal fibroblasts using agents such as TGFβ1 or complement." (PMID 34768796, 2021). "We conclude that ectopic expression of PDX1 reduces the migration potential of cancer cells, by increasing the adhesive properties of cells and reducing the sensitivity to TGFβ1-induced EMT." (PMID 34503200, 2021). "Regarding the TME, TGFβ1 seemed to be important in cancer invasion and metastasis, as well as angiogenesis." (PMID 34884420, 2021). "The data obtained suggest that ectopic expression of PDX1 reduces the migration potential of cancer cells, in particular, by increasing the adhesive properties of cells and reducing the sensitivity of cells to TGFβ1-induced EMT." (PMID 34503200, 2021). "For example, the level of the EGFR/TGFB1 pair was overexpressed from ductal cell-fibroblast to cancer cell-fibroblast communication." (PMID 34326696, 2021). "TGFβ1 is secreted by cancer cells or fibroblasts in an inactive form, which consists of the 12.5-kDa carboxy-terminal region of TGFβ1 and a 25-kDa amino-terminal latency-associated peptide (LAP) joined by noncovalent bonding." (PMID 34621667, 2021). "The same cancer cells inhibited by TGFβ1 to reduce their growth and metastatic potential in the early phases of tumor development progressively escape this suppressive effect and use growth factors to drive metastasis." (PMID 34071145, 2021). "In colorectal cancer, upregulation of TGFβ1 gene expression led to poor prognosis in patients with cancer." (PMID 34095135, 2021). "Similar to CD36, high expression of TGFβ1 was found in the hepatocytes adjacent to cancer cells compared to distal hepatocytes." (PMID 34376784, 2021). "According to our observations, PDX1 ectopic expression of PDX1 reduced the migration potential of cancer cells, in particular, by increasing the adhesive properties of cells and reducing the sensitivity of cells to TGFβ1-induced EMT." (PMID 34503200, 2021). "In summary, these data suggest signaling crosstalk between hepatocytes and cancer cells that regulates the expression of both TGFβ1 and RUNX1, which is orchestrated through TSP1." (PMID 34376784, 2021). "We further screened the activated ligand-receptor pairs between ductal cells and these two stroma-cell types and defined several cancer-associated pairs, such as EGFR/TGFB1, ANXA1/FPR3, EREG/EGFR, and ICAM1/AREG." (PMID 34326696, 2021). "On the other hand, TGFβ1 induced cancer progression and metastasis and inhibited antitumor immunity, thus promoting cancer." (PMID 34095135, 2021). "The expression levels of TGFB2 and TGFB3 were extremely low, while the TGFB1 expressed dominantly in the monocytes in blood and the macrophages in cancer tissues." (PMID 35069521, 2021). "As reported, CD44 expression level is positively correlated with PD-L1, PD-1, IL10, and TGFB1 expression in some cancers." (PMID 35187044, 2021). "Analysis of cytokines showed that the IL10 and TGFB1 (TGFβ) were overexpressed in EMT-high tumors of most cancer types, and both of these are known to suppress antitumor immunity in TIME." (PMID 35096592, 2021).
cancer (continued). "This transition occurs under stimulation by TGFβ1 secreted by cancer cells in response to anticancer drug treatment." (PMID 33498521, 2021). "To find out if RUNX1 can modulate TGFβ1 function in these processes, we performed various in vitro experiments and treated cancer cells with either recombinant TGFβ1 or co-cultured with hepatocyte (IHH) cells, upon RUNX1 inhibition." (PMID 34376784, 2021). "Increased TGFB1 mRNA or TGFβ1 protein level in cancer tissue or patient plasma was identified as a prognostic factor for rapid progression and poor survival outcome." (PMID 35127538, 2021). "We further observed that ectopically expressed TGFβ1 can behave as either endogenous or exogenous TGFβ1, depending on the cancer type." (PMID 33802809, 2021). "It was found that TGFβ1 levels in CAFs that were lower than the median were sufficient to promote cancer cell proliferation and inhibit cell apoptosis, while higher TGFβ1 levels inhibited antitumor immunity." (PMID 34095135, 2021). "Factors such as tissue transglutaminase 2 (TG2), a cross-linking enzyme, and TGFβ1, when transferred by cancer EVs to distant fibroblasts, trigger the production of matrix proteins, periostin, and fibronectin to alter the ECM for successful metastasis." (PMID 34943937, 2021). "In SMAD3-silenced NK cells (NK-92-S3KD), TGFβ1-mediated immunosuppression was blocked, inhibiting cancer progression in mouse models with human hepatoma and melanoma." (PMID 34025641, 2021). "Cancer cells undergo EMT in the presence of transforming growth factor beta 1 (TGF-β1), inducing a phenotypic transformation from a differentiated adherent epithelial phenotype to a more motile mesenchymal phenotype that contributes to metastatic invasion." (PMID 34834307, 2021). "We also assessed the top genes differently expressed between penta- and tetra-cultures, where we identified several ECM molecules previously associated with poor prognosis in cancer (COL11A1, TNC, TGFβ1)." (PMID 34189439, 2021). "Taken together, these experiments indicate that TGFβ1 signaling can induce RUNX1 expression in cancer cells through TGFβRII." (PMID 34376784, 2021). "Via cytokines (e.g., transforming growth factor beta 1 (TGF-β1)), Treg cells suppress cancer-specific effector immune cells (CD8+ T cells) and decrease the antitumour capacity of the host." (PMID 34834295, 2021). "Secondly, using Pearson's correlation analysis of GSE53625 and TCGA data, we found that 1609 genes were positively correlated with TGFβ1 expression in ESCC cancer tissues (r > 0.15, FDR < 0.05)." (PMID 34218518, 2021). "Among them, TGFβ1 has shown the ability to induce a varied set of responses in cancer progression and metastasis." (PMID 34095135, 2021). "The HMC3 cells were stimulated with a cytokine cocktail known to originate from cancer cells, that was comprised of interleukins IL-4, IL-13, IL-10, growth factors TGFβ1/TGFβ2, and chemokine CCL2." (PMID 34566949, 2021). "The cross-talking between TGFβ1 signaling and other pathways has also been identified in multiple processes, such as cancer invasion, stem-cell self-renewal, and lineage-specific differentiation." (PMID 33430164, 2021). "Stimulation by soluble or cancer-derived exosome-tethered TGFβ1, or increased mechanical tension in the tissue, results in fibroblast to myofibroblast differentiation." (PMID 33804204, 2021). "For example, TGFβ1 plays an important role in cancer migration due to its mediation of CAF contractility and MMP secretion, where CAFs produce MMPs that destroy the structure of the TME architecture." (PMID 34884420, 2021). "We demonstrated that m6A methylation played at least three distinct roles in TGFβ1-induced EMT regulation—modulating TGFB1 mRNA decay and translation, TGFβ1 activation, and Snail expression—suggesting the multiple roles of m6A in cancer progression regulation." (PMID 31991845, 2020).
cancer (continued). "Parallel with the wide range of roles, the dysregulation of TGFβ1 expression and activity contributes to a number of disease states, including many cancers, cardiovascular disease, and musculoskeletal disease." (PMID 33371439, 2020). "We further tested the potential effects of the METTL3/TGFβ1/Snail axis on the in vivo progression of cancer." (PMID 31991845, 2020). "As we have mentioned, Smad7 is a TGFβ1 signaling inhibitor and has been reported to inhibit TGFβ1-induced cancer cell EMT and metastasis." (PMID 33085646, 2020). "TGFβ1 also contributes directly to hepatocarcinogenesis via auto- and paracrine activities in the cancer epithelial cells." (PMID 32899119, 2020). "We showed the potential of the chip in cancer research by observing subtle changes in the cellular properties of transforming growth factor beta 1 (TGF-β1)-induced epithelial–mesenchymal transition (EMT) A549 cells." (PMID 34567668, 2020). "Smad7 is a TGFβ1 signaling inhibitor and has been reported to inhibit TGFβ1-induced cancer cell epithelial-mesenchymal transition (EMT) and metastasis." (PMID 33085646, 2020). "LHTD4 inhibited the migration of MDA-MB-231 cancer cells by blocking the transforming growth factor beta 1 (TGF-β1) signaling pathway and the CXCL12-CXCR4 axis." (PMID 32538273, 2020). "Several clinical inhibitors targeting the TGFβ1 pathway in cancer have been developed that are either ligand traps or block ligand-receptor interaction or inhibit the kinase activity of the TGFβ receptors." (PMID 33150300, 2020). "And KEGG pathway analysis showed TGFB1 was related to pathways in cancer, TGF-beta signaling pathway, focal adhesion, signaling pathways regulating pluripotency of stem cells, regulation of actin cytoskeleton, Hippo signaling pathway, and shigellosis." (PMID 33062039, 2020). "TGFβ signaling plays an important role in mesenchymal transition in cancer, and TGFβ1/3 and TβRII are the three TGFβ signaling genes within the list of 840 transcriptomic signature genes that are used to classify GBM subtypes." (PMID 32944398, 2020). "It has been found that transforming growth factor-beta 1 (TGF-β1) induces epithelial mesenchymal transition (EMT) in various cancer cells, promoting motility and invasiveness." (PMID 32050534, 2020). "Specifically in H1975 cells, we observed a marked increase in expression of TGFB1, a known inducer of clusterin expression in cancer cells." (PMID 32533048, 2020). "Together, these data suggested that METTL3/ TGFβ1/Snail axis regulates the in vivo progression of cancer." (PMID 31991845, 2020). "In this study, we investigate the potential effects of m6A on the TGFβ1-induced EMT of cancer cells." (PMID 31991845, 2020). "ASCs secrete factors that are potentially associated with cancer development and progression, including IGF-1, transforming growth factor beta 1 (TGFβ1), vascular endothelial growth factor (VEGF), hepatocyte growth factor (HGF), and IL-8." (PMID 33105727, 2020). "We also found a positive correlation between ABCC4 expression and TGFβ1/2 receptors and its ligand TGFβ2, which were shown to be involved in epithelial conversion induction in cancers." (PMID 33261018, 2020). "Such an effect action has also been described in conditioned medium from macrophages exposed to UV-killed cancer cells, which display TGFβ1-induced EMT inhibition, migration, and metastasis." (PMID 32264958, 2020). "The TGFβ1 levels detected in 143-B EVs were comparable to levels in EVs isolated from other cancer cell lines." (PMID 32751693, 2020). "qRT-PCR showed enhanced expression of METTL3 and TGFβ1 in metastasized lung tumors compared to that in the primary tumors isolated from MMTV-PyMT mice, confirming that METTL3/TGFβ1 triggers cancer progression and metastasis." (PMID 31991845, 2020). "When neovascular sprouting is induced, loss of TSP-1 and secretion of new ECM proteins (POSTN, TNC, TGFβ1) trigger reawakening of cancer cells." (PMID 31963820, 2020).
cancer (continued). "Cancer cells produce transforming growth factor beta 1 (TGF-β1), which by phosphorylation activates p38 mitogen-activated protein kinase (p38 MAPK kinase) in CAFs, which drives glycolysis in them." (PMID 32290479, 2020). "An important role in the metabolic reprogramming of cancer cells is played by the TGF-β1 (Transforming growth factor beta 1) through the upregulation of Smad, p38 MAPK and PI3K/AKT pathways." (PMID 33008042, 2020). "The role of TGFβ1, which is ubiquitously expressed, in cancer development and progression has been extensively studied." (PMID 32393769, 2020). "Signals including the epidermal growth factor (EGF), transforming growth factor beta 1 (TGF-β1), and thrombospondin 1 mediate the proliferation and quiescence of cancer cells during dissemination." (PMID 31900168, 2020). "Since we were particularly interested in RAC1B regulation of TGFβ signaling and carcinoma cells predominantly express TGFβ1, we focussed on TGFB1 in all further experiments." (PMID 33260366, 2020). "Our data suggest that RAC1B induces SMAD7 by promoting its deubiquitination and establishes this Smad as one of RAC1B’s downstream effectors in negative regulation of ALK5 and TGFβ1-induced cell migration in mesenchymal-type carcinoma cells." (PMID 32545415, 2020). "The functional outcome of the TGFβ1 response is cell context-dependent and, in advanced carcinoma, enhances cellular invasion, promotes dissemination to distant tissues, increases angiogenesis, and promotes immune evasion." (PMID 33150300, 2020). "Based on RNA-seq data from the cancer cell line encyclopedia, HepG2 cells expressed much higher levels of TGFB1 than TGFB2 or TGFB3." (PMID 31462641, 2019). "In line with these molecular alterations, CD166− cells treated with TGFβ1 acquired a relative resistance to erlotinib and cancer stem cell-like phenotype, including the ability of sphere formation and CD133 expression." (PMID 31138318, 2019). "TGFβ1 signaling and EMT are strictly interconnected in cancer since TGFβ1 controls cell motility and the mesenchymal properties of the cells." (PMID 31752957, 2019). "TGFβ1 is the most abundant, most widely studied, and most commonly dysregulated isoform in cancer, and thus, will be the focus of this review." (PMID 31438626, 2019). "The treatment of TGF-β in cancer cells results in the genetic alteration of important genes through transcriptional regulation, primarily targeting TGFB1 and TGFB3, which are repressed by c-Myc and Oct4/Klf4, respectively." (PMID 31275381, 2019). "Epithelial-mesenchymal transition (EMT), characterized by decreased E-cadherin expression and increased vimentin expression, mediates cancer cell invasion and metastasis, and transforming growth factor-β1 (TGFβ1) can independently induce EMT in cancer cells." (PMID 30992007, 2019). "The TGFB1 pathway is pro-metastatic in late stages of cancer and, like PF4, TGFB1 has been linked to platelet activity in cancer patients." (PMID 31215484, 2019). "The growth factors in the bone microenvironment stimulate cancer cell growth, and the cancer cells induce bone resorption and release more growth factors from the bone matrix, such as TGFβ1, which in turn induce osteoblast activity." (PMID 31753020, 2019). "Transforming growth factor beta 1 (TGFβ1) is an important cytokine in cancer progression, and plays a very important role in migration and metastasis of various cancers." (PMID 29367650, 2018). "The three cases were 1 EBV+ case in which approximately 10% of cancer cells were positive for LAP (TGFβ1) and 2 EBV− cases in which approximately 50 and 20% of cancer cells expressed LAP (TGFβ1)." (PMID 29594353, 2018). "It has been shown that TGFβ1 can increase VEGF-C expression in certain cancer cells via Smad2/3 binding to the VEGF-C promoter region." (PMID 29995950, 2018).
cancer (continued). "To exclude the possibility that the observed increases in S100A10 were limited to A549 cells, we treated multiple cancer cell types known to undergo EMT in response to TGFβ1 treatment." (PMID 30237490, 2018). "The presence of TGFB1 increases the ability of cancer cells to metastasize by promoting invasion and migration." (PMID 30115852, 2018). "Cancer cell expression of TGFβ1 in the previous study is consistent with the present study on control GCs." (PMID 29594353, 2018). "While TGFβ1 inhibits cell growth at an early stage of carcinogenesis, it supports metastasis formation in late‐stage cancer." (PMID 30004628, 2018). "The present study is designed to analyze the in situ localization of TGFβ1 in cancers with prominent lymphocytic infiltrate." (PMID 29594353, 2018). "The present histopathological study analyzed the in situ expression of TGFβ1 in human Ly-rich GCs to show that its expression is observed mainly in immune cells, but only focally in cancer cells." (PMID 29594353, 2018). "Noteworthy, even brief transitory communication between cancer cells and normal fibroblasts leads to an elevated release of transforming growth factor beta 1 (TGF-β1) by activated fibroblasts in response to cancer cell presence." (PMID 30200265, 2018). "More importantly, TGFβ1 elevates both the expression level of cancer stem-like cell markers and anchorage-dependent colony formation ability in TGFβ1 sensitive lines." (PMID 29995950, 2018). "This indicates that the expression of TGFβ1 in immune cells correlated with the degrees of immune cell infiltrate in cancer tissue." (PMID 29594353, 2018). "Our data revealed abundant expression of TGFβ1 in immune cells with contact to Treg cells in lymphoid stroma, which is consistent with the notion that TGFβ1 is one of the immunosuppressive factors in cancer stroma." (PMID 29594353, 2018). "While these tests confirmed that fibroblasts also secreted TGFβ1, a significant contribution of cancer cell-derived TGFβ1 was observed in cancer cell-fibroblast co-cultures." (PMID 28515430, 2017). "Transforming growth factor-beta 1 (TGF-β1) is a regulatory cytokine which suppresses immune function in cancers and in chronic viral infections." (PMID 29312460, 2017). "Cancer is a major clinical implication in which the joint activities of TNFα + TGFβ1 on MSCs are very relevant." (PMID 28553282, 2017). "For example, organotypic 3D cultures that recapitulated the early dissemination of OC into peritoneal mesothelium revealed that cancer cells, via secretion of transforming growth factor beta-1 (TGFβ1), induce mesothelial cells to synthesize fibronectin." (PMID 28320418, 2017). "Concentration of TGFβ1 that was secreted from MDA cancer cells was around 250 pg/ml following 24 h of incubation (27 and our observations)." (PMID 28515430, 2017). "Mechanistically, platelet-derived TGFβ1 acts via the p-Smad pathway to induce a phenotypic conversion in cancer cells, from epithelial to mesenchymal-like cells, capable of invading extracellular matrices, migrating and surviving in the blood circulation." (PMID 28737696, 2017). "For example, TGFβ1, first described as a transforming growth factor, is also a potent growth inhibitor at benign stages of cancer and promotes metastasis, genetic heterogeneity, and drug resistance in aggressive carcinomas." (PMID 28649369, 2017). "To confirm this role for TGFβ1, we repeated our naïve T cell stimulations with cancer cell supernatants, in the context of TGFβ blockade mediated by a blocking anti-TGFβ antibody." (PMID 28239749, 2017). "Recent published reports indicate that the pro-tumoral activities of TNFα and TGFβ1 are manifested through their impact on the cancer cells and on cells of the TME, such as MSCs that populate the tumors." (PMID 28553282, 2017). "JAK/STAT3 is a major signalling pathway for leptin action and JAK/STAT3 can be a signalling intermediate for EMT via TGFB1 in cancer." (PMID 28542577, 2017).